RNU6-291P (RNA, U6 small nuclear 291, pseudogene)
Gene: Small nuclear RNA gene on chromosome 1 (11,226,254 to 11,226,360, forward strand). Ensembl gene ENSG00000207451.
Homologues: Orthologues: chimpanzee U6 (98% identical), macaque U6 (95% identical), rat LOC120097304 (81% identical), pig U6 (77% identical). Paralogues in human: RNU6-589P (87% identical), RNU6-15P (86% identical), RNU6-41P (86% identical), RNU6-820P (86% identical), RNU6-1011P (85% identical), RNU6-1131P (85% identical), RNU6-1152P (85% identical), RNU6-12P (85% identical), RNU6-13P (85% identical), RNU6-16P (85% identical), RNU6-26P (85% identical), RNU6-31P (85% identical), and 1283 more.